CLCA2 (chloride channel accessory 2)
Description:
Plays a role in modulating chloride current across the plasma membrane in a calcium-dependent manner, and cell adhesion. Involved in basal cell adhesion and/or stratification of squamous epithelia. May act as a tumor suppressor in breast and colorectal cancer. Plays a key role for cell adhesion in the beginning stages of lung metastasis via the binding to ITGB4.
Synonyms: CaCC-3; CACC3; CLCRG2; CACC
Tractability: Small molecule: it belongs to a druggable protein family. Antibody: its Gene Ontology location is reachable by antibodies, with high confidence; UniProt places it where antibodies can reach, with medium confidence; UniProt predicts a signal peptide or a membrane-spanning region; the Human Protein Atlas places it where antibodies can reach.
Gene: Protein-coding gene on chromosome 1 (86,424,171 to 86,456,553, forward strand). Ensembl gene ENSG00000137975.
Subcellular location: Cell membrane; Basal cell membrane; Cell junction; Secreted (Calcium-activated chloride channel regulator 2, 109 kDa form)
Subcellular location (Human Protein Atlas): Cell Junctions; Plasma membrane; Nucleoplasm
Pathways (Reactome):
Transport of small molecules: Stimuli-sensing channels
Gene Ontology:
Molecular function: chloride channel activity; intracellularly calcium-gated chloride channel activity; metalloendopeptidase activity; ligand-gated monoatomic ion channel activity
Biological process: monoatomic ion transmembrane transport; chloride transmembrane transport; chloride transport
Cellular component: cell junction; plasma membrane; anchoring junction; basal plasma membrane; extracellular region
Genetic constraint (gnomAD): Loss-of-function variants: 67 observed, 71.8 expected, observed/expected ratio (o/e) 0.93, 90% interval 0.76 to 1.14. The upper end of that interval is the gene's LOEUF score, 1.14, which puts it in group 5 of 6, group 1 being the genes least tolerant of losing a copy. Missense variants: 967 observed, 1,049.5 expected, observed/expected ratio (o/e) 0.92, 90% interval 0.87 to 0.97. Synonymous variants: 382 observed, 372.96 expected, observed/expected ratio (o/e) 1.02, 90% interval 0.94 to 1.12.
Homologues: Orthologues: chimpanzee CLCA2 (99% identical), dog CLCA2 (85% identical), rabbit CLCA2 (82% identical), pig CLCA2 (80% identical), guinea pig CLCA2 (74% identical), rat Clca2 (73% identical), mouse Clca2 (72% identical). Paralogues in human: CLCA1 (43% identical), CLCA4 (42% identical).
Diseases named in the same sentence as CLCA2 in open-access papers:
CLCA2 is named in the same sentence as 47 diseases in open-access papers, as found by Europe PMC text mining. Sharing a sentence is not in itself a finding about the gene and the disease. The quoted sentences say what the papers report.
breast carcinoma (23 papers, 2006 to 2024). "Investigations have shown the association of CLCA2 with the development of breast cancer and metastasis." (PMID 34236536, 2021). "For instance, studies have validated that the loss of CLCA2 expression is closely associated with tumorigenicity and the metastasis of breast cancer." (PMID 28974231, 2017). "CLCA2 is strongly associated with epithelial differentiation in breast and is downregulated in many breast cancers, most dramatically in the mesenchymal subtype." (PMID 26930581, 2016). "Loss of CLCA2 expression has been reported to be associated with poor clinical outcomes in patients with breast cancer; however, the impact of reduced expression of CLCA2 on the survival in patients with other types of cancer has not yet been reported." (PMID 25548429, 2014). "In fact, the tumorigenicity of breast cancer was related with a loss of CLCA2." (PMID 24053408, 2013). "Since it has recently been revealed that loss of CLCA2 promotes the epithelial to mesenchymal transition (EMT) in breast cancer cells, we next examined whether the transcriptional profile of EMT markers might be changed in SCC of the lung using data from the TCGA database." (PMID 25548429, 2014). "It was initially confirmed that CLCA2 is downregulated in breast cancer, and that its overexpression in breast cancer cells results in weakened tumorigenicity." (PMID 38528613, 2024). "It has been shown that the expression of α6β4 integrin on human breast cancer cells promotes lung metastasis due to interaction with human CLCA2 (hCLCA2) expressed on the endothelial cell of the inner surface of pulmonary arteries, arterioles, and venules." (PMID 36769251, 2023). "The expression of CLCA2 has been verified to correlate with poor clinical outcomes in the breast cancer patients, while the impact of reduced CLCA2 expression on survival has not yet been studied in the patients with other types of cancer." (PMID 33936227, 2021). "Our gene network analysis indicated that two protein transporters including APOB and CLCA2 contribute in the breast cancer." (PMID 34236536, 2021). "Associations between CLCA2, SPIC, and MIR4311 and overall and breast cancer specific survival in the Detroit AA cohort." (PMID 32298355, 2020). "Three genes (CLCA2, SPIC, MIR4311) were associated with overall and breast cancer specific survival in this discovery cohort." (PMID 32298355, 2020). "One study reported that the roles of CLCA2 in breast cancer include inhibiting proliferation, promoting apoptosis or senescence, and maintaining the cytotoxic response of cancer cells in response to doxorubicin treatment." (PMID 29463274, 2018). "In breast cancer, Lu-ECAM-1 (CLCA2) was capable of facilitating lung metastasis by interactions with integrin α6β4 expressed on breast cancer cells." (PMID 29703238, 2018). "Early in 1999, Gruber A.D. and his colleagues determined that the expression of CLCA2 was frequently lost in breast cancer and that the re-expression of CLCA2 repressed tumor metastasis in vitro and in vivo." (PMID 28974231, 2017). "Accordingly, patients with low CFTR, CLCA2 or CLCA4 mRNA abundance in breast cancer specimens have higher odds of developing metastases and a decreased relapse-free survival (green)." (PMID 27618016, 2016). "CLCA2 is frequently downregulated in breast cancers by promoter methylation, and ectopic expression in a breast cancer cell line inhibited tumor formation by tail vein injection and xenograft." (PMID 26930581, 2016). "CLCA2 that shares 63% sequence similarity with CLCA1 has been suggested to be a breast cancer tumor-suppressor gene." (PMID 21542898, 2011). "Of note, CLCA2 represents a tumor suppressor gene that has been shown to promote apoptosis in a variety of cancer models, including breast cancer." (PMID 21159190, 2010).
breast carcinoma (continued). "Similarly, numerous tumor-associated genes, including COL1A2, PD-L1, HOXB cluster genes, and CLCA2, are epigenetically regulated in breast cancer cells." (PMID 36768307, 2023). "It should be noted that CLCA2 plays a critical role in the epithelial differentiation of breasts and the process of promoting methylation will also lead to the downregulation of CLCA2 in breast cancers." (PMID 34236536, 2021). "We also found that the CLCA2 gene can be considered in breast cancer." (PMID 34236536, 2021). "While the CLCA2 has clear implications for invasion and metastasis in breast cancer, the mechanism by which increased CLCA2 tumor expression may be related to worse clinical outcomes for women with TNBC is unclear." (PMID 32298355, 2020). "CLCA2 was reported as a tumor suppressor and disregulated in breast cancer." (PMID 29463274, 2018). "The CLCA2 Cl− channel regulator exerts tumor-suppressing function in breast cancer." (PMID 27618016, 2016). "Moreover, reduced CLCA2 expression is associated with transcriptional changes of the EMT marker in SCC of the lung as shown in this study and in breast cancer as shown in a previous study." (PMID 25548429, 2014). "Besides Cl- intracellular channels, the Ca+ activated Cl- channel CLCA2 was downregulated in breast cancer and is a candidate tumor suppressor gene." (PMID 24053408, 2013). "It has been concluded that CLCA2 may act as a tumor suppressor in breast cancer." (PMID 28974231, 2017). "Our current study revealed that loss of CLCA2 protein expression was a poor prognostic factor in female patients with lung SCC, indicating that the CLCA2 expression status is associated with a poor prognosis, not only in patients with breast cancer but also in those with SCC of the lung." (PMID 25548429, 2014). "Finally, based on co-expression network analysis, we screened 7 potential gene markers related to metabolic characteristic index, of which CLCA2, REEP6, SPDEF, and CRAT can be used to indicate breast cancer prognosis." (PMID 35875026, 2022). "CLCA2 is frequently down-regulated in breast cancer and is a candidate tumor suppressor gene for negative regulation of breast cancer cell migration and invasion." (PMID 29463274, 2018).
lung carcinoma (5 papers, 2014 to 2024). "The ΔCt values of CLCA2 in lung cancer patients were 3.99-17.52 (mean: 10.55) and 1.94-14.02 (mean: 7.742) in healthy controls." (PMID 39130876, 2024). "Then from a total of 30 genes selected by the screening, we chose CLCA2 (chloride channel accessory 2), examined its expression status in 396 lung cancers, and found that CLCA2 is a sensitive and specific marker of SCC." (PMID 25548429, 2014). "Among the selected genes, the CLCA2 gene, which is involved in chloride conductance, was selected and its protein expression status was evaluated in a total of 396 cases of primary lung cancer from Hamamatsu University Hospital." (PMID 25548429, 2014). "Subsequently, analysis of gene expression data from more than 1000 types of cancer tissues revealed that the expression of CLCA2 was significantly reduced in bladder cancer, esophageal cancer, lung cancer, high-grade nasopharyngeal carcinoma, colorectal cancer, lymphoma tissue, and prostate cancer." (PMID 38528613, 2024). "The cytoplasmic and/or membranous localization of CLCA2 detected in the lung cancer cells in the present study implies that cellular localization is convenient for potential expression of the physiological role of CLCA2 in the regulation of chloride conductance and cell adhesion." (PMID 25548429, 2014). "In conclusion, 30 candidate genes that were specifically expressed depending on the lung cancer histology were selected, and, among these, we identified CLCA2 as a novel immunohistochemical marker useful for differential diagnosis between SCC and ADC of the lung." (PMID 25548429, 2014). "They hypothesized that CLCA2 might be a marker for lung cancer detection." (PMID 39130876, 2024). "Among the genes, we chose the CLCA2 gene, which is involved in chloride conductance and whose protein expression in lung cancer is yet to be characterized, and evaluated its protein expression status in 396 cases of primary lung cancer at Hamamatsu University Hospital." (PMID 25548429, 2014). "In the current research, we utilized an RT-PCR-based assay for the identification of HMGB3, survivin, CLCA2, CK7, ASH1, and L587S gene expressions in lung cancer patients." (PMID 39130876, 2024). "The sensitivity and specificity of CLCA2, SPATS2, ST6GALNAC1, and Adipophilin in adequate subtyping of poorly differentiating lung cancer and reaching accurate diagnosis was 100%." (PMID 33936227, 2021). "The combination of biomarkers of CLCA2, SPATS2, ST6GALNAC1, and Adipophilin may lead to an appropriate subtyping of lung cancer and reaching accurate diagnosis with the highest sensitivity and specificity." (PMID 33936227, 2021). "It has been reported that CLCA2 mRNA is more strongly expressed in SCC of the lung as compared to that in ADC of the lung; however, the CLCA2 protein expression status in lung cancer had not yet been investigated." (PMID 25548429, 2014).
breast tumors (4 papers, 2013 to 2020). "CLCA2 is clustered in the 1p31 region, which is frequently downregulated in breast tumors, and loss of hCLCA2 promotes EMT and indicates higher risk of metastasis in breast epithelium." (PMID 29463274, 2018). "CLCA2 expression has been found to be downregulated in breast tumors, whereas CLCA2 expression is known to inhibit migration and invasion while simultaneously promoting mesenchymal-to-epithelial transition in cancer cell lines." (PMID 32298355, 2020).
lung adenocarcinoma (4 papers, 2017 to 2024). A carcinoma that arises from the lung and is characterized by the presence of malignant glandular epithelial cells. "The one study that reported associations between CLCA2 and survival in cancer reported worse disease-free survival associated with increased CLCA2 expression in early stage lung adenocarcinoma, which is comparable to our findings." (PMID 32298355, 2020).
asthma (3 papers, 2012 to 2023). "Chloride Channel Accessory 2 (CLCA2) has been implicated in airway diseases and contributes to secretory functions of airway epithelial cells in physiological and pathological processes, particularly in respiratory diseases like asthma and COPD." (PMID 38062491, 2023). "We observed interactions between CLCA1 and asthma DERs located downstream and an asthma-SE located upstream encompassing the CLCA2 transcriptional start site." (PMID 33362848, 2020).
cervical cancer (3 papers, 2022 to 2024). A primary or metastatic malignant neoplasm involving the cervix. "The results showed that the mRNA and protein expression of CLCA2 in cervical cancer cells was significantly decreased, especially in C33A cell line." (PMID 36280802, 2022). "These in vivo findings coincided with the in vitro changes observed in the cell models, demonstrating that CLCA2 inhibits cervical cancer growth and EMT." (PMID 36280802, 2022). "We first detected the mRNA and protein levels of CLCA2 in normal cervical cell line H8 and cervical cancer cell lines SiHa, HeLa and C33A." (PMID 36280802, 2022). "In our study, we found the expression of CLCA2 in cervical cancer cells was significantly decreased, and overexpression of CLCA2 inhibits the proliferation, migration and invasion, and promotes apoptosis of cervical cancer cells." (PMID 36280802, 2022). "To further validate the effect of CLCA2 on the growth of cervical cancer cells in vivo, we established a C33A cell tumorigenic model." (PMID 36280802, 2022). "In this study, we first detected the expression of CLCA2 in cervical cancer cell lines siha,hela, and C33A." (PMID 36280802, 2022). "Our results confirmed that the expression of CLCA2 was significantly decreased in cervical cancer cells." (PMID 36280802, 2022). "After overexpression of CLCA2 in cervical cancer cells, cell proliferation, migration, invasion and apoptosis were detected." (PMID 36280802, 2022). "In conclusion, overexpression of CLCA2 inhibited the progression of cervical cancer in vivo and in vitro." (PMID 36280802, 2022). "Then, we detected the changes of EMT related markers after overexpression of CLCA2 in cervical cancer cells." (PMID 36280802, 2022). "This study preliminarily explored the role of CLCA2 in cervical cancer, in order to provide a certain basis for further clinical application." (PMID 36280802, 2022). "CLCA2 inhibits the proliferation, migration and invasion of cervical cancer." (PMID 38152044, 2024). "Overexpression of CLCA2 inhibited the progression of cervical cancer in vivo and in vitro." (PMID 36280802, 2022). "This may provide a theoretical basis for CLCA2 as a new indicator of clinical diagnosis and prognosis of cervical cancer or as a potential target of drug therapy." (PMID 36280802, 2022). "In this study, we found that overexpression of CLCA2 up-regulated the expression of E-cadherin and down-regulated the expression of N-cadherin, indicate that overexpression of CLCA2 gene can block epithelial mesenchymal transition (EMT) in cervical cancer cells." (PMID 36280802, 2022). "It has confirmed that CLCA2 can regulate cell function through p38 / JNK / ERK pathway, and our results also show that CLCA2 can also regulate the pathway in cervical cancer cells, but the specific mechanism still needs to be further clarified." (PMID 36280802, 2022). "Furthermore, the overexpression of CLCA2 inhibits EMT via the inactivation of the p38/JNK/ERK signaling pathway and also inhibits the proliferation, migration, and invasion of cervical cancer cells." (PMID 38203460, 2023). "However, the regulatory role of CLCA2 in cervical cancer has not been studied." (PMID 36280802, 2022). "However, up to now, the regulatory role of CLCA2 in cervical cancer has not been clarified." (PMID 36280802, 2022).
nasopharyngeal carcinoma (3 papers, 2018 to 2024). A carcinoma arising from the nasopharyngeal epithelium. "Low levels of CLCA2 mRNA and protein have been identified in nasopharyngeal carcinoma (NPC) S18 and 5-8F cells, whereas overexpressed CLCA2 inhibits FAK/ERK signaling in these cells." (PMID 35205604, 2022). "Together, these results demonstrate the importance of CLCA2 in the down-regulation of nasopharyngeal carcinoma cellular migration, invasion, and metastasis." (PMID 29463274, 2018). "In our study, overexpression of CLCA2-negative cell lines significantly reduced tumorigenicity and metastasis, suggesting a tumor suppressor role for CLCA2 in nasopharyngeal carcinoma." (PMID 29463274, 2018). "To examine whether CLCA2 silencing induces nasopharyngeal carcinoma motility via FAK/ERK activation, we tested the motility of nasopharyngeal carcinoma cells following inhibition of FAK and the downstream ERK1/2 pathway." (PMID 29463274, 2018). "CLCA2 suppressed NPC proliferation and metastasis by inhibiting the FAK/ERK signaling pathway, CLCA2 may serve as a potential predictor for distant metastasis and early diagnosis of nasopharyngeal carcinoma." (PMID 29463274, 2018).
atopic dermatitis (2 papers, 2023 to 2024). "For example, abnormal activation of the p38/JNK-ATF2 pathway promotes high expression of CLCA3A2 and CLCA2 in the epidermal cells of mice with atopic dermatitis (AD) and the keratinocytes of patients with AD, inducing keratinocyte apoptosis." (PMID 38528613, 2024). "Additionally, experimental research indicated that higher environmental humidity alleviates the symptoms of atopic dermatitis-like mice by regulating CLCA2 expression in keratinocytes." (PMID 37921044, 2023).
cervical squamous cell carcinoma (2 papers, 2022). A squamous cell carcinoma arising from the cervical epithelium. "Calcium-activated chloride channel 2 (CLCA2) expression was reported to be significantly downregulated in cervical squamous cell carcinoma, and was found to be negatively correlated with the enrichment of immune cells, especially with B cells, macrophage cells, and dendritic cell." (PMID 35875026, 2022).
cystic fibrosis (2 papers, 2016 to 2021). Autosomal recessive disorder caused by pathogenic variants in the CFTR gene (cystic fibrosis transmembrane conductance regulator), which encodes a chloride and bicarbonate channel expressed in epithelial cells, and follow the diagnosis criteria. "Early characterization of Clca2 protein structure and expression pattern indicated that Clca2 might be a regulator of cystic fibrosis." (PMID 34869368, 2021).
glioblastoma (2 papers, 2020 to 2024). The most malignant astrocytic tumor (WHO grade IV). "In this work, CLCA2 silencing also resulted in cells’ increased viability after TMZ treatment, indicating this is also an exciting target for clinical therapy for glioblastoma patients, when used in combination with TMZ." (PMID 33271924, 2020).